SASH3 (SAM and SH3 domain containing 3)
Description:
May function as a signaling adapter protein in lymphocytes.
Synonyms: CXorf9; SLY; 753P9; SH3D6C; HACS2; IMD102
Tractability: Antibody: the Human Protein Atlas places it where antibodies can reach. PROTAC: its protein half-life has been measured.
Gene: Protein-coding gene on chromosome X (129,779,949 to 129,795,201, forward strand). Ensembl gene ENSG00000122122.
Subcellular location (Human Protein Atlas): Plasma membrane; Nuclear bodies; Nucleoplasm
Gene Ontology:
Biological process: positive regulation of adaptive immune response; positive regulation of B cell proliferation; positive regulation of immunoglobulin production; regulation of intracellular signal transduction
Cellular component: cytoplasm; nucleus
Gene-disease validity (ClinGen):
ClinGen rates the evidence that SASH3 causes each of these diseases.
combined immunodeficiency, X-linked (X-linked): Definitive.
Homologues: Orthologues: chimpanzee SASH3 (99% identical), pig SASH3 (96% identical), dog SASH3 (95% identical), mouse Sash3 (95% identical), macaque SASH3 (94% identical), rat Sash3 (94% identical), guinea pig SASH3 (94% identical), tropical clawed frog sash3 (58% identical), zebrafish sash3 (50% identical). Paralogues in human: SASH1 (44% identical), SAMSN1 (35% identical).
Diseases named in the same sentence as SASH3 in open-access papers:
SASH3 is named in the same sentence as 38 diseases in open-access papers, as found by Europe PMC text mining. Sharing a sentence is not in itself a finding about the gene and the disease. The quoted sentences say what the papers report.
breast carcinoma (4 papers, 2020 to 2023). "Some studies had shown that SASH3 was a potential prognostic factor for breast cancer patients and associated with the lymphocytic infiltrating tumor." (PMID 35756681, 2022). "Consistent with our present data, SASH3 has been reported to be associated with prognosis of breast cancer by other bioinformatics analysis recently, but it has not been verified by further experiments." (PMID 35047378, 2021). "SASH3 has also been reported by other bioinformatic analyses as a tumor microenvironment-related gene with prognostic value for breast cancer." (PMID 37963845, 2023). "Recent studies have demonstrated that SASH3 was downregulated in breast cancer and correlated with a good prognosis." (PMID 35756681, 2022). "As a Lymphocyte specific immune recruitment gene (LYM) gene, SASH3 was related to lymphocytic infiltrating tumor and had good prognosis of breast cancer." (PMID 33274208, 2020). "Previous studies have shown that SASH3 was positively correlated with T cells in breast cancer." (PMID 35756681, 2022). "It has been confirmed that SASH3 was a potential prognostic factor for breast cancer patients." (PMID 35756681, 2022). "Some studies had shown that SASH3 was a potential prognostic factor for breast cancer patients." (PMID 33274208, 2020). "It was suggested that SASH3 may affect the immune microenvironment of breast cancer patients." (PMID 33274208, 2020).
diverticulitis (3 papers, 2018 to 2024). An infection that develops in the diverticula of the intestinal tract. "They further identified four immune-regulatory hub genes: RAS protein activator-like 3 (RASAL3), protein tyrosine phosphatase, receptor type C (PTPRC), inositol polyphosphate-5-phophatase D (INPP5D), and SAM and SH3 domain-containing 3 (SASH3) that were associated with diverticulitis." (PMID 32635383, 2020). "Hub genes RASAL3, SASH3, PTPRC, and INPP5D were found to upregulate immune response-associated transcripts in the sigmoid colons of chronic, recurrent diverticulitis patients as identified by Schiefer et al25." (PMID 38831715, 2024). "This built on earlier work, by the same team, which suggested the hub genes RASAL3, SASH3, PTPRC and INPP5D within the brown module eigengene were highly correlated (r = 0.67, P = 0.0004) with diverticulitis." (PMID 38831715, 2024).
head and neck squamous cell carcinoma (2 papers, 2022 to 2024). A squamous cell carcinoma that arises from any of the following anatomic sites: lip and oral cavity, nasal cavity, paranasal sinuses, pharynx, larynx, and salivary glands. "IKZF1 is involved in lymphoid differentiation and its co-expression with SASH3 and IL10RA is associated with good prognosis of head and neck squamous cell carcinoma." (PMID 39107857, 2024). "We found that SASH3 expression was increased in breast invasive carcinoma (BRCA), cholangiocarcinoma (CHOL), head and neck squamous cell carcinoma (HNSC), kidney renal clear cell carcinoma (KIRC), and kidney renal papillary cell carcinoma (KIRP) tissues compared with adjacent normal tissues." (PMID 35756681, 2022).
immune deficiency (2 papers, 2022 to 2025). "In conclusion, we presented a case of SASH3 deficiency characterized by combined immune deficiency, metaphyseal dysplasia and intellectual impairment." (PMID 40947476, 2025). "SASH3 deficiency may represent a mild or moderate form of this condition, although SASH3 is the causative gene of combined immune deficiency." (PMID 40947476, 2025).
lung adenocarcinoma (2 papers, 2022 to 2024). A carcinoma that arises from the lung and is characterized by the presence of malignant glandular epithelial cells. "Also the high expression of SNX20, which is connected with SASH3 and CD53 through the focal adhesion-encoding gene LPXN, has been associated with immune-active TIME and better OS in lung adenocarcinoma patients." (PMID 39107857, 2024). "Finally, forced SASH3 expression inhibited lung adenocarcinoma (LUAD) cell proliferation and cell migration." (PMID 35756681, 2022). "Finally, the growth curve, transwell, and flow cytometry were used to determine the biological function of SASH3 on lung adenocarcinoma (LUAD) cells." (PMID 35756681, 2022).
lung carcinoma (2 papers, 2021 to 2022). "At the same time, we found that the staining strength of the SASH3 antibody in lung cancer tissues of China Medical University was higher in paracancerous tissues but relatively lower in tumor tissues." (PMID 34234827, 2021). "The results showed that SASH3 was positively correlated with the content of CD8+ T lymphocytes in lung cancer, glioma, liver cancer, and other cancers." (PMID 34234827, 2021). "Moreover, SASH3 is associated with gene regulatory sites (such as WAS and CD53) in lung cancer, which has diagnostic value for lung cancer metastasis." (PMID 36408131, 2022). "Therefore, SASH3 has important clinical and biological significance in the microenvironment of lung cancer." (PMID 36408131, 2022). "The intersection was taken to screen out that SASH3 and CD53 were tumor purity-related prognostic genes of lung cancer." (PMID 34234827, 2021). "There is currently a lack of research on the relationship between EVI2B, SASH3, and PLEK with lung cancer." (PMID 34234827, 2021).
X-linked combined immunodeficiency (2 papers, 2021 to 2022). "In a recent study, SASH3 deficiency was described as a novel X-linked combined immunodeficiency with immune dysregulation, associated with impaired TCR signaling and thymocyte survival in humans." (PMID 35464398, 2022).
B cell lymphoma (1 paper, 2020). "Finally, SASH3, reported to be expressed in T and B cell lymphoma cell lines, is involved in signal transduction affecting immune system development and immune response." (PMID 32679859, 2020).
bladder urothelial carcinoma (1 paper, 2022). "Meanwhile, low expression of SASH3 in cancer was observed in bladder urothelial carcinoma (BLCA), colon adenocarcinoma (COAD), esophageal carcinoma (ESCA), LUAD, lung squamous cell carcinoma (LUSC), and rectum adenocarcinoma (READ)." (PMID 35756681, 2022).
cervical cancer (1 paper, 2021). A primary or metastatic malignant neoplasm involving the cervix. "SASH1, containing highly similar protein structure with SASH3, functions as a tumor suppressor to inhibit the development of many cancers, such as colon cancer, gastric cancer, BRCA, and cervical cancer." (PMID 35047378, 2021).
Intellectual disability (1 paper, 2025). "Here we identified a male case with a pathogenic SASH3 variant (c.1039C>T [p.Arg347Cys]) who presented with osteogenesis imperfecta, intellectual disability and recurrent infections." (PMID 40947476, 2025).
intellectual impairment (1 paper, 2025). "In addition, the unique clinical manifestations noted in this patient, metaphyseal dysplasia and intellectual impairment, have not been reported in all individuals with SASH3 deficiency." (PMID 40947476, 2025).
invasive breast carcinoma (1 paper, 2021). A carcinoma that infiltrates the breast parenchyma. "In this study, we first analyzed the correlation between SASH3 expression and prognosis of invasive breast cancer by using COX analysis." (PMID 35047378, 2021).
testicular germ cell tumor (1 paper, 2022). A germ cell tumor arising from the testis. "Additionally, we also found that SASH3 was downregulated in COAD, LUAD, and testicular germ cell tumors (LIHC)." (PMID 35756681, 2022).
viral infection (1 paper, 2022). "Two severe episodes of viral infection alerted us to a possible T-cell defect, and genetic testing led to SASH3 deficiency." (PMID 35464398, 2022).
tumor (9 papers, 2018 to 2024). "The association between SASH3 expression and gene mutation, DNA methylation, immune cells infiltration, immune checkpoints, tumor mutation burden (TMB), and microsatellite instability (MSI) were analyzed using data from the TCGA database." (PMID 35756681, 2022). "Univariate analysis showed that three factors, including SASH3 expression, number of lymph nodes, and tumor size, were significantly associated with RFS in 467 invasive BRCA patients (p < 0.05)." (PMID 35047378, 2021). "To examine the potential role of SASH3 regulating tumor cell migration, we performed transwell assays." (PMID 35756681, 2022). "This evidence indicated that SASH3 can regulate the immune cell infiltration and thus play a role in tumor regulation." (PMID 35756681, 2022). "For tumor immune cell infiltration, we found that SASH3 expression was positively correlated with the infiltration levels of T cell CD8+, T cell CD4+, Neutrophil, Myeloid dendritic cell, Macrophage, and B cell in 31 types of cancers." (PMID 35756681, 2022). "Third, we did not conduct the in vivo experiments to validate the function of SASH3 in the tumor metastasis and TME regulation of LUAD." (PMID 35756681, 2022). "Recently, SASH3, one of the HF-DEGs identified here was also reported to be a tumor microenvironment-related gene with prognostic value in BRCA by other bioinformatics analysis." (PMID 35047378, 2021). "Clinical phenotype and immune phenotype assessments of the coexpressed genes showed that SASH3 negatively correlated with tumor purity and positively correlated with CD8+ T lymphocytes." (PMID 34234827, 2021). "The results suggested that CD4, CD53, EVI2b, PLEK, and SASH3 correlated with tumor purity, immune score, CD8+ T cells, and clinical phenotypes." (PMID 34234827, 2021). "Five coexpressed genes (CD4, CD53, EVI2B, PLEK, and SASH3) were identified as tumor purity coexpressed genes that negatively correlated with tumor purity." (PMID 34234827, 2021). "Indeed, the WGCNA of TCGA-LUAD cohort revealed that patients with this tumor phenotype had down-regulated an extensive gene network led by SASH3 and including IKZF1, IL10RA, CD53 and SNX20, all involved in immune activation." (PMID 39107857, 2024). "We found that overexpression of SASH3 inhibited tumor cell growth and cell migration." (PMID 35756681, 2022). "Overexpression of SASH3 inhibited tumor cell growth and cell migration." (PMID 35756681, 2022). "However, the potential molecular mechanisms of SASH3 in tumor growth and metastasis need to be explored in further studies." (PMID 35756681, 2022). "Together, these data suggest that SASH3 acts as a novel tumor suppressor in LUAD." (PMID 35756681, 2022). "Moreover, we analyzed the association between SASH3 expression and TMB, MSI, tumor microenvironment (TME), immune cell infiltration, and immune-related gene expression in human cancer." (PMID 35756681, 2022). "We showed that overexpression of SASH3 inhibited tumor cell growth compared to the control cells." (PMID 35756681, 2022). "Our results confirmed that SASH3 expression was positively correlated with 28 tumor-infiltrating lymphocytes, 45 immune stimulators, 24 immune inhibitors, 41 chemokines, 18 receptors, and 21 major histocompatibility complex (MHC) molecules in different cancer types." (PMID 35756681, 2022). "In addition, SASH3 was one of the co-expressed factors related to tumor purity, which was significantly negatively correlated with tumor purity, but positively correlated with CD8+ T lymphocytes and immune score." (PMID 36408131, 2022). "Therefore, we speculate that SASH3 may serve as a tumor suppressor to inhibit the occurrence and development of invasive BRCA." (PMID 35047378, 2021). "Multivariate analysis including SASH3 expression, number of lymph nodes, tumor size, and AJCC stage (all p < 0.2) showed that SASH3 expression and number of lymph nodes were significantly associated with prognosis of invasive BRCA patients (p < 0.05)." (PMID 35047378, 2021).
tumor (continued). "These coexpression factors (SASH3 and CD53) can be used to classify tumor purity phenotypes and to predict clinical outcomes." (PMID 34234827, 2021). "We finally identified SASH3 and CD53 as tumor purity-related prognostic factors." (PMID 34234827, 2021).
cancer (5 papers, 2019 to 2022). A tumor composed of atypical neoplastic, often pleomorphic cells that invade other tissues. "For the prognostic and diagnostic value of SASH3 in pan-cancer, we found that high expression of SASH3 was not only linked to poor OS in ESCC, LAML, LGG, and UVM, but also associated with better OS in CESC, HNSC, LUAD, SARC, SKCM, THYM, and UCEC." (PMID 35756681, 2022). "SASH3 expression was correlated with TMB in 28 cancer types and associated with MSI in 22 cancer types, while there was a negative correlation between SASH3 expression and DNA methylation in diverse human cancer." (PMID 35756681, 2022). "Next, we explored the correlation between SASH3 expression and drug response in different cancer cell lines from GDSC and CTRP." (PMID 35756681, 2022). "To further determine the potential molecular mechanism by which SASH3 affects cancer progression, we performed KEGG and GSEA analyses." (PMID 35756681, 2022). "This study comprehensively analyzed the role of SASH3 in pan-cancer, including expression level, clinical features, prognostic values, DNA methylation, and mutation status of SASH3." (PMID 35756681, 2022). "In conclusion, our finding discovered the potential function of SASH3 in pan-cancer for the first time." (PMID 35756681, 2022). "To examine the application of SASH3 in cancer prognosis, we built a nomogram for predicting the OS, DSS, and PFS of LUAD patients in the TCGA cohort." (PMID 35756681, 2022). "First, we examined the expression level of SASH3 in human cancers in the TCGA cohort with the corresponding normal tissue as control." (PMID 35756681, 2022). "In summary, these results demonstrated that SASH3 expression was significantly negatively correlated with sensitivity to many drugs in different cancer cell lines." (PMID 35756681, 2022). "We found that SASH3 expression was positively correlated with the infiltration levels of six major immune cells in 31 types of cancers." (PMID 35756681, 2022). "We showed above that SASH3 expression was correlated with the prognosis of patients with different cancer types." (PMID 35756681, 2022). "This study improves our understanding of the correlation between SASH3 and human cancer, but some limitations still exist." (PMID 35756681, 2022). "According to the TCGA pan-cancer atlas, a three-dimensional image of the SASH3 protein was acquired." (PMID 35756681, 2022). "In this study, we found that the expression of SASH3 was correlated significantly with the stroma score in 27 cancer types, the microenvironment score, and immune score in 32 cancer types." (PMID 35756681, 2022). "To ascertain the prognostic role of SASH3 in different types of cancer, we ascertained the OS, DSS, and relapse-free survival (RFS) in human cancer types." (PMID 35756681, 2022). "In this study, we comprehensively examined the expression, dysregulation, and prognostic significance of SASH3, and the correlation with clinicopathological parameters and immune infiltration in pan-cancer." (PMID 35756681, 2022). "MYO1F, SASH3 and KLHL41 are the candidate pathogenic genes that shared with multi-cancers in this paper." (PMID 31888692, 2019). "We utilized the GCSA database to explore the DNA methylation level of SASH3 in human cancer." (PMID 35756681, 2022). "Therefore, SASH3 can be used as a promising molecular predictor to evaluate the prognosis of cancer patients as well as a therapeutic target in the clinical detection of LUAD." (PMID 35756681, 2022). "All of these lines of evidence confirmed for the first time that SASH3 plays an extremely crucial role in cancer progression and that SASH3 may be an important biomarker for the diagnosis, treatment, and prognosis of human cancer." (PMID 35756681, 2022). "Our findings confirmed that SASH3 may be a biomarker for the prognosis and diagnosis of human cancer." (PMID 35756681, 2022). "SASH3 expression was positively correlated with immune checkpoint-related genes in 31 cancer types." (PMID 35756681, 2022).